ITPRIPL1 (ITPRIP like 1)
Description:
Functions as a ligand of CD3E, inhibiting TCR-CD3 complex signaling to regulate T cell activation. Induces stable CD3E-NCK1 binding, thereby preventing the CD3E-ZAP70 interaction and subsequently inhibiting the activation of the downstream ERK-NFkB signaling cascade and calcium influx.
Synonyms: KIAA1754L; D1B
Tractability: Antibody: UniProt places it where antibodies can reach, with high confidence; its Gene Ontology location is reachable by antibodies, with high confidence; UniProt predicts a signal peptide or a membrane-spanning region. PROTAC: ubiquitination databases record sites on it.
Gene: Protein-coding gene on chromosome 2 (96,324,977 to 96,330,517, forward strand). Ensembl gene ENSG00000198885.
Subcellular location: Cell membrane
Gene Ontology:
Molecular function: protein binding; receptor ligand activity
Biological process: negative regulation of T cell receptor signaling pathway; signal transduction
Cellular component: membrane; plasma membrane
Genetic constraint (gnomAD): Loss-of-function variants: 28 observed, 42.27 expected, observed/expected ratio (o/e) 0.66, 90% interval 0.49 to 0.91. The upper end of that interval is the gene's LOEUF score, 0.91, which puts it in group 3 of 6, group 1 being the genes least tolerant of losing a copy. Missense variants: 638 observed, 733.92 expected, observed/expected ratio (o/e) 0.87, 90% interval 0.81 to 0.93. Synonymous variants: 251 observed, 293.13 expected, observed/expected ratio (o/e) 0.86, 90% interval 0.77 to 0.95.
Homologues: Orthologues: chimpanzee ITPRIPL1 (99% identical), dog ITPRIPL1 (93% identical), pig ITPRIPL1 (90% identical), rat Itpripl1 (88% identical), mouse Itpripl1 (86% identical), guinea pig ITPRIPL1 (82% identical). Paralogues in human: ITPRIP (29% identical), ITPRIPL2 (17% identical), CGAS (11% identical), MAB21L4 (11% identical), MAB21L3 (10% identical), MB21D2 (10% identical), MAB21L2 (10% identical), TMEM102 (10% identical), MAB21L1 (9% identical).
Diseases named in the same sentence as ITPRIPL1 in open-access papers:
ITPRIPL1 is named in the same sentence as 37 diseases in open-access papers, as found by Europe PMC text mining. Sharing a sentence is not in itself a finding about the gene and the disease. The quoted sentences say what the papers report.
breast carcinoma (4 papers, 2021 to 2024). "The data indicated that the aberrant circulating hypermethylated CCDC181, GCM2 and ITPRIPL1 detected in the plasma samples were also significantly present in the associated tumor tissues of breast cancer patients (Spearman’s rho = 0.702, 0.497 and 0.634, all p < 0.001)." (PMID 33803633, 2021). "The mRNA expression levels of the ITPRIPL1 gene vary significantly across multiple types of cancer and significantly reduced in breast cancer." (PMID 39211744, 2024). "Significant differences in the validation set of samples were found for seven genes; the combination of the four genes GCM2, ITPRIPL1, CACNA1E, DLGAP2 (AUC = 0.99) showed the highest diagnostic value based on logistic regression for all breast cancer samples." (PMID 37628841, 2023). "Few studies have reported the clinical significance and application of aberrant CCDC181, GCM2 and ITPRIPL1 methylation in breast cancer." (PMID 33803633, 2021). "The box plot demonstrates an increase in CCDC181, GCM2 and ITPRIPL1 in tumors of Taiwanese breast cancer patients compared with the adjacent normal tissues using the paired-sample Wilcoxon test (Z score −9.02, −7.94, −8.65, p < 0.001)." (PMID 33803633, 2021). "Hypermethylation of CCDC181, GCM2 and ITPRIPL1 was observed in different subgroups of breast cancer patients, including in individuals of different races and in various menopause states as well as with different tumor stages and histological types." (PMID 33803633, 2021). "Circulating methylated CCDC181, GCM2 and ITPRIPL1 was detected in 57.1–84.6% of ductal carcinoma in situ (DCIS) tumors from breast cancer patients." (PMID 33803633, 2021). "Hypermethylation of CCDC181, GCM2 and ITPRIPL1 was found in more than 80% of patients with lower tumor histologic grades, and in 70% of early-stage breast cancer among all subtypes of breast cancer patients." (PMID 33803633, 2021). "As promising biomarkers, circulating methylated CCDC181, GCM2 and ITPRIPL1 are expected to improve the detection of breast cancer." (PMID 33803633, 2021). "ITPRIPL1 promoter methylation was also observed in 83.3% of Stage 0 breast cancer patients, 77.1% of patients with smaller-sized tumors and 74.3% of patients without lymph node metastasis." (PMID 33803633, 2021). "The heatmap revealed hypermethylation of CCDC181, GCM2 and ITPRIPL1 in tumors of breast cancer patients compared with adjacent normal tissues from the Taiwanese and TCGA cohort (respectively)." (PMID 33803633, 2021). "Aberrant methylation patterns of the CCDC181, GCM2 and ITPRIPL1 genes are highly prevalent in Western and Taiwanese breast cancer patients, suggesting that they are potential biomarkers for early prediction in Western and Asian countries." (PMID 33803633, 2021). "Circulating methylated CCDC181, GCM2 and ITPRIPL1 analysis could be combined with ultrasound to facilitate the early detection of breast cancer." (PMID 33803633, 2021). "Finally, the most breast cancer-specific biomarkers, circulating methylated CCDC181, GCM2 and ITPRIPL1 (CGIm), were identified in patients with early-stage breast cancer." (PMID 33803633, 2021). "Therefore, the profiles of CCDC181, GCM2 and ITPRIPL1 in breast cancer were selected for further analysis." (PMID 33803633, 2021). "Therefore, we suggested that the methylation pattern of circulating CCDC181, GCM2 and ITPRIPL1 could be combined with mammography or/and ultrasonography and applied for the early prediction of breast cancer." (PMID 33803633, 2021). "The aberrant methylation patterns of the CCDC181, GCM2 and ITPRIPL1 genes means that they are potential biomarkers for the detection of early BC and can be combined with breast imaging data to achieve higher accuracy, sensitivity and specificity, facilitating breast cancer detection." (PMID 33803633, 2021). "The methylation patterns of the CCDC181, GCM2, ITPRIPL1, ENPP2, LOC643719, ZNF177 and ADCY4 genes were further determined in plasma samples from healthy and early breast cancer patients." (PMID 33803633, 2021).
breast carcinoma (continued). "Aberrant methylation patterns of the CCDC181, GCM2, ITPRIPL1, ENPP2, LOC643719, ZNF177 and ADCY4 genes were identified and further evaluated in paired tumor and normal tissues of breast cancer patients." (PMID 33803633, 2021). "Most breast cancer-specific circulating methylated CCDC181, GCM2 and ITPRIPL1 biomarkers were found in the plasma." (PMID 33803633, 2021). "Combined analysis of CCDC181, GCM2 and ITPRIPL1 was performed by Recursive Partitioning and Regression Trees (RPART) using 57 breast cancer and 134 health plasma samples from the subjects." (PMID 33803633, 2021). "The breast cancer specificity of methylated CCDC181, GCM2, ITPRIPL1, LOC643719 and ZNF177 ranged from 64.3 to 100%, indicating lower false-positive signals." (PMID 33803633, 2021). "Aberrant methylation of CCDC181, GCM2, ITPRIPL1, ENPP2, LOC643719, ZNF177 and ADCY4 was found in breast cancer patients from the Taiwanese and TCGA cohorts using the methylation array." (PMID 33803633, 2021). "In this study, we carry out automatic detection of circulating cell-free methylated DNA, including GCM2, ITPRIPL1 and CCDC181, and find a pattern that can detect early breast cancer more accurately compared with currently used biomarkers." (PMID 33803633, 2021). "To further determine the methylation pattern of breast cancer tissues in the Taiwanese cohort, we analyzed the methylation levels of CCDC181, GCM2, ITPRIPL1, ENPP2, LOC643719, ZNF177 and ADCY4 in tumors and adjacent normal tissue in Taiwanese breast cancer patients." (PMID 33803633, 2021). "The results for seven candidate genes—CCDC181, GCM2, ITPRIPL1, ENPP2, LOC643719, ZNF177 and ADCY4—were successfully validated by sequencing and stable detection in ccfDNA from the plasma of Taiwanese patients with breast cancer." (PMID 33803633, 2021). "To further investigate whether the use of circulating methylated CCDC181, GCM2 and ITPRIPL1 biomarkers could improve the detection of breast cancers, we combined the ultrasonography BI-RADS (3 and 4a) and circulating methylated CCDC181, GCM2 and ITPRIPL1 levels." (PMID 33803633, 2021).
glioma (4 papers, 2023 to 2025). A benign or malignant brain and spinal cord tumor that arises from glial cells (astrocytes, oligodendrocytes, ependymal cells). "Future work should include in vitro and in vivo experiments to further elucidate the biological functions and underlying mechanisms of ITPRIPL1 in glioma." (PMID 40792394, 2025). "This included evaluating ITPRIPL1 expression levels in glioma, its association with clinicopathological features, prognostic significance, immune landscape, targeted drug sensitivity, and underlying biological functions." (PMID 40792394, 2025). "Furthermore, an increase in ITPRIPL1 expression was associated with a marked reduction in OS among glioma patients." (PMID 40792394, 2025). "In the TCGA dataset, subgroup analyses indicated that ITPRIPL1 expression was higher in high‐grade glioma, IDH wild‐type glioma, and glioma without 1p/19q codeletion." (PMID 40792394, 2025). "To further validate the potential role of ITPRIPL1 in immune responses and regulation in glioma, we performed gene set variation analysis to calculate the enrichment scores of immune‐related processes in both the TCGA and CGGA datasets." (PMID 40792394, 2025). "A nomogram was subsequently constructed and validated to assess the integrated prognostic impact of ITPRIPL1 expression on glioma patients." (PMID 40792394, 2025). "A comprehensive analysis was conducted using the TCGA, CGGA and GEO databases, covering the expression level of ITPRIPL1 in glioma, clinical characteristics, prognostic value, immunological value, targeted drug screening, and biological functions." (PMID 40792394, 2025). "Although ITPRIPL1 has been less studied in glioma, it has been reported in breast and lung cancers to influence therapeutic response by regulating immune checkpoint molecules, synergizing with PD-L1 to suppress T cell function, and recruiting M2 macrophages." (PMID 40661083, 2025). "This suggests ITPRIPL1 as a novel target for overcoming immunotherapy resistance in glioma, for example, through the development of ITPRIPL1/PD-L1 bispecific antibodies." (PMID 40661083, 2025). "This study systematically investigated the role of ITPRIPL1 in glioma using datasets from TCGA, CGGA, and GEO." (PMID 40792394, 2025). "Recent studies have identified ITPRIPL1, a newly reported CD3ε‐inhibitory ligand, as a suppressor of T cell activation, thereby facilitating tumor immune evasion and offering a novel avenue for immunotherapeutic intervention in glioma." (PMID 40792394, 2025). "This study reveals a dual biological role of ITPRIPL1 in glioma." (PMID 40792394, 2025). "Therefore, ITPRIPL1 not only holds promise as a novel prognostic biomarker for glioma, but also emerges as a potential therapeutic target in the context of immunotherapy." (PMID 40792394, 2025). "The results showed positive correlations between ITPRIPL1 and these immunosuppressive checkpoints, suggesting that ITPRIPL1 may contribute to immune evasion in glioma." (PMID 40792394, 2025). "Molecular docking results indicated that these sensitive drugs can directly bind to the ITPRIPL1 protein, suggesting that ITPRIPL1 may serve as a potential therapeutic target in glioma." (PMID 40792394, 2025). "Therefore, elucidating the immunomodulatory role of ITPRIPL1 in glioma may offer valuable insights for diagnosis and therapeutic intervention." (PMID 40792394, 2025). "Notably, IMPA2, SOD3, CD274, ITPRIPL1, and RAC2 displayed relatively negative correlations across multiple cancers, including glioma." (PMID 40852729, 2025).
lung carcinoma (2 papers, 2021 to 2025). "However, hypermethylation of ITPRIPL1 has been shown in lung cancer patients." (PMID 33803633, 2021).
breast tumors (1 paper, 2021). "The data suggested that methylated circulating CCDC181, GCM2 and ITPRIPL1 were mostly derived from primary tumors and could serve as new postsurgical monitoring biomarkers for the detection of residual tumors, with the exception of primary breast tumors." (PMID 33803633, 2021).
cholera (1 paper, 2022). "The region with the strongest signal of selection, located on chromosome 2 and encompassing five genes (NRNP200, CIAO1, ITPRIPL1, NCAPH, and TMEM127) was also the region showing the strongest association with cholera, with the top associated SNPs located between the genes NRNP200 and ITPRIPL1." (PMID 35925921, 2022).
mesothelioma (1 paper, 2024). A usually malignant and aggressive neoplasm of the mesothelium which is often associated with exposure to asbestos. "We observed the mRNA expression levels of ITPRIPL1 varied significantly across clinicopathological stages in mesothelioma (MESO), LIHC, SKCM, thyroid carcinoma (THCA), and TGCT (P < 0.05)." (PMID 39211744, 2024).
tumor (10 papers, 2015 to 2026). "The accuracy and precision of the ITPRIPL1 positive rate as an immunohistochemical diagnostic biomarker suggests the potential of ITPRIPL1 as an auxiliary method for tumor diagnosis." (PMID 38188019, 2023). "Considering the positive correlation between ITPRIPL1 expression and tumor stages, we further explored the possibility of setting ITPRIPL1 as an aided diagnostic index." (PMID 38188019, 2023). "Furthermore, we computed the correlation of ITPRIPL1 expression with tumor mutation burden (TMB), microsatellite instability (MSI), and immune-related genes." (PMID 39211744, 2024). "The negative correlation between ITPRIPL1 and CD8 expression suggests that ITPRIPL1 expression may indicate a “cold” tumor microenvironment as ITPRIPL1 is associated with a low CD8+ signal." (PMID 38188019, 2023). "CD3 ligand 1 (CD3L1, ITPRIPL1), an emerging immune checkpoint, sustains immune privilege in the testis and facilitates tumor immune evasion." (PMID 42141271, 2026). "Elevated ITPRIPL1 expression was positively correlated with higher tumor grade and poorer clinical outcomes." (PMID 40792394, 2025). "The results revealed that ITPRIPL1 expression was positively correlated with most immune functions, particularly with the “Negative regulation of T cell mediated immune responses to tumor cells” in the TCGA dataset." (PMID 40792394, 2025). "Analysis using GEPIA and TIMER revealed that ITPRIPL1 is highly expressed in various tumor types compared to normal tissues, with a particularly significant upregulation observed in GBM." (PMID 40792394, 2025). "RNA-seq datasets downloaded from HPA, TCGA and GTEx databases were employed to explore ITPRIPL1 expression in various human normal and tumor tissues." (PMID 39211744, 2024). "Inositol 1,4,5-triphosphate receptor-interacting protein-like 1 (ITPRIPL1), a single-pass transmembrane protein, functions as a natural ligand of CD3ε, leading to the reduction of T cell activity and fostering tumor growth." (PMID 39211744, 2024). "The ITPRIPL1-CD3ε axis formed by the binding of ITPRIPL1 as a ligand on the surface of tumor cells with CD3ε can inhibit TCR-CD3 complexes signal transmission." (PMID 39342365, 2024). "In this study, we analyzed public data from HPA, TCGA, and GTEx and showed the expression of ITPRIPL1 in various human normal and tumor tissues." (PMID 39211744, 2024). "Therapeutic antibodies targeting ITPRIPL1 can effectively enhance the cytotoxicity of tumor-specific T cells and achieve tumor growth control and are expected to be promising therapeutic targets for various types of tumors." (PMID 39342365, 2024). "To validate the IHC-staining specificity of the anti-ITPRIPL1 antibody, we analyzed local tumor tissues with different DAB signal intensities." (PMID 38188019, 2023). "The application of anti-ITPRIPL1 reveals overexpression of ITPRIPL1 in NSCLCs, with correlation with immune infiltration, tumor progression, clinical prognosis, and tumor diagnosis." (PMID 38188019, 2023). "To evaluate the correlation between ITPRIPL1 expression and tumor progression, we further collected the detailed stage information of our patients." (PMID 38188019, 2023). "This study reports that a newly discovered immune checkpoint, ITPRIPL1, can also be leveraged as a proteomic biomarker for tumor diagnosis, prognosis prediction, and relation to CD8+ T cell infiltration." (PMID 38188019, 2023). "The representative images showing different DAB signal intensities in different local tumor tissues confirmed the specificity of the anti-ITPRIPL1 antibody." (PMID 38188019, 2023). "To precisely evaluate the ITPRIPL1 expression in NSCLC patients, we collected 75 groups of paired patient tissue samples (the tumor tissue and respective paracancerous tissue) and performed immunohistochemistry with our anti-ITPRIPL1 antibody." (PMID 38188019, 2023). "In our previous study, we have found ITPRIPL1 can impair T cell function and downregulate anti-tumor immune response (submitted)." (PMID 38188019, 2023).